CD4 (CD4 molecule)
Diseases named in the same sentence as CD4 in open-access papers (continued):
Sharing a sentence is not in itself a finding about the gene and the disease.
tumor (continued). "Moreover, vaccination with irradiated B16-mBD2 promoted the infiltration of CD8+ and CD4+ T, NK cells and macrophages in the tumor tissues." (PMID 22348070, 2012). "The tumor appears to affect the frequency of CTLs and Th cells, as demonstrated by an increase in Th cells and a decrease in CTLs as well as a higher CD4/CD8 ratio, and thereby inhibiting the anti-tumorigenic CTL response and promoting a pro-tumorigenic environment." (PMID 23251433, 2012). "Thus, xeno-priming with HER2 protein can induce homologous rat neu-specific CD4+ T-cell responses; this induction is important for tumor vaccination studies using rat neu-expressing tumor models." (PMID 22397502, 2012). "Furthermore, it has been demonstrated in a mouse model that only tumour-reactive CD4+ T cells have been found to ensure efficient effector CTLs recruitment at the tumour site." (PMID 23284752, 2012). "Flow cytometric evaluation of spleens of mice that had rejected a secondary tumor rechallenge showed an enhancement in the CD4+CD44+ and CD8+CD44+ T cell memory markers as well as an enhanced secretion of IFNγ by memory T cells in response to OVA stimulation in vitro." (PMID 22815789, 2012). "Because the immunological status of MUC1.Tg mice injected with tumor cells expressing MUC1 has not been thoroughly characterized, we compared T cell subpopulations in B6 and MUC1.Tg mice, particularly the CD4+ effector T cells and Treg cells that infiltrated the tumor." (PMID 23028615, 2012). "To clarify the relative contributions of CD4 and CD8 T cells in mediating control of tumor growth by female splenocytes, we performed a mix-and-match experiment using male and female donors that were depleted in vivo with antibodies against either CD4 or CD8." (PMID 22493742, 2012). "However, emerging evidence indicates that CD4+ T cells also develop cytotoxic activity to directly participate in cytolysis of tumor or infected cells." (PMID 23145026, 2012). "To determine whether tumour protection is mediated by CD4+ or CD8+ T cells, we transferred 107 CD4+ T cells or 1.5×106 CD8+ T cells from B16F10 challenged AIRE KO or AIRE WT mice into naïve hosts, followed by challenge with B16F10 the following day." (PMID 22506061, 2012). "The distinct CD4+ T-cell subsets have varied impact on tumor growth." (PMID 22400040, 2012). "In addition, transfer of idiotype-specific CD4+ T cells has been shown to be protective against tumor challenge." (PMID 22649466, 2012). "In the last years preventive and therapeutic vaccination strategies using viral and tumor antigens (Ags) have been developed aiming at activation of naïve or expansion of spontaneous viral and tumor Ag-specific memory CD4+ T cells; leading to the first FDA approved therapeutic antitumor vaccine." (PMID 22879946, 2012). "Whereas CD4+ T cells alone clearly have the potential to effectively eradicate tumors, the majority of published studies indicate that the optimal antitumor effects are achieved when CD4+ T cells act in concert with tumor-reactive CD8+ T cells, macrophages, or NK cells." (PMID 22400040, 2012). "Precise identification of Tregs will allow a better comparison of their levels to potentially beneficial subsets (for tumour elimination) such as CD4 effector (CD25int) or CD8 central and effector memory T cells, particularly for those that have been activated in the patients (CD38+)." (PMID 24213326, 2012). "Recent data from our and other groups demonstrate that such NK-DC interaction promotes the subsequent induction of tumor-specific responses of CD4+ and CD8+ T cells, allowing NK cells to act as “helper” cells in the development of the type 1 DCs in responses against cancer." (PMID 22481968, 2012). "In contrast to the general increase of CD4+ T cells, the frequency of Foxp3 expressing cells within the CD4+ population was 4-fold lower in the vaccine-treated tumor than in the untreated tumor, while it was comparable in peripheral blood and spleen between the two groups." (PMID 23071764, 2012).
tumor (continued). "Additionally, Flynn and Stockinger studied the role of specific CD4+ populations in the subcutaneous LK35 tumor model with Rag−/−γc−/− mice that lack all lymphocytes and NK cells." (PMID 22400032, 2012). "Tumor-specific CD4+ T cells have a central function in the immune response against cancer." (PMID 22649466, 2012). "Rejection and/or reduced tumor growth were mediated by tumor specific CD4+ TH and CD8+ CTL." (PMID 22849661, 2012). "Indeed, even if some tumor antigen specific CD4 Treg clones were also found to secrete a diverse panel of cytokines such as IFN-γ, GM-CSF, TNF and IL5 or IL4 and IL10, in vitro, none of them was able to secrete IL2." (PMID 23284752, 2012). "In addition, treatment with tumor antigen specific CD4 or CD8 T cells or their combination yielded a significant improvement in survival of CD200 positive tumor bearing mice." (PMID 22319630, 2012). "Likewise in human esophageal cancer, simultaneous occurrence of Hsp70 expression and B- and plasma-cell infiltration into tumors was an indicator of good prognosis, even exceeding the benefits of tumor infiltration of CD4+ and CD8+ T cells." (PMID 23056925, 2012). "However, the tolerogenic nature of the tumor milieu progressively renders CD4+ effector T cells dysfunctional, characterized by sustained expression of PD1 and heightened apoptosis." (PMID 22400040, 2012). "CD4+ T helper cells have been shown to support tumor cell clearance through various mechanisms." (PMID 24710413, 2012). "Indeed, tumour-reactive CD4+ T helper 1 cells (Th1) produce several cytokines (such as IFN-fγ, TNF-α and IL-2) essential for the induction of cell-mediated immunity against tumours." (PMID 23284752, 2012). "Furthermore, CD4+ T cells provide help for the maintenance and expansion of CTLs by secreting cytokines, and can eradicate tumor cells directly." (PMID 24213236, 2012). "Interestingly, CD4+ FoxP3+ Helios+ Treg appeared to be relatively enriched in the tumor parenchyma as compared to corresponding spleens." (PMID 22479644, 2012). "In addition, increased CD4+CD25+ Tregs in the tumor microenvironment of HCC were found to be correlated with tumor size and vascular invasion." (PMID 22272696, 2012). "Thus, for these cells to be fully functional and migrate to the tumor site where they can then express their cytolytic activity they require the efficient CD4 support in which IL-2 and IL-21 production appears essential." (PMID 22383042, 2012). "Interestingly, the tumor growth and survival period of the CD4+ T cell-depleted mice was slightly slower and significantly longer than that of the CD8+ T cell-depleted mice." (PMID 22348070, 2012). "Furthermore, they indicate that tumor infiltration by CD4+ or FOXP3+ cells is devoid of prognostic relevance." (PMID 22471961, 2012). "Tumor sections were stained for expression of tumor infiltrating CD4+ and CD8+ T cells." (PMID 22159900, 2012). "Many tumor models also require help from CD4 T cells to achieve full tumor rejection." (PMID 22911764, 2012). "Previous studies suggested that low avidity T cells remain ignorant of antigen expression and therefore do not mount a successful tumor-specific response, while others suggest that CD4+ T cell help enhances low avidity T cell function allowing for some degree of tumor destruction." (PMID 22359647, 2012). "The vaccine therapeutic efficacy was associated with tumor-specific killing activity, high frequency of IFN-γ secreting CD4+ T and CD8+ T cells, increased intratumoral number of CD4+ T and CD8+ T cells, and a decrease in the number of CD4+FoxP3+ Treg cells." (PMID 22870329, 2012). "Similarly, the frequency of CD69+ CD4+ cells was also significantly elevated in tdLN of high tumor-burdened animals compared to the low tumor burden group (p < 0.005; unpaired two-tailed Student’s t test)." (PMID 22674057, 2012).
tumor (continued). "In addition, treatment with tumor antigen specific CD4 or CD8 T cells or their combination yielded a survival advantage for CD200 positive tumor bearing mice over mice bearing CD200-negative tumors." (PMID 22319630, 2012). "Given that CD8+ T cell-derived TNFα and IFNγ can sensitize tumor stroma and mediate bystander tumor eradication, we speculate that polyfunctional CD4+ effector T cells have the same effect because these cells can produce these two cytokines simultaneously." (PMID 22400040, 2012). "Tumor-specific CD4+ T cells recognize antigenic peptides presented by MHC class II molecules." (PMID 22649466, 2012). "On the other hand, tumor infiltration by T-lymphocytes subsets endowed with immuno-regulatory or suppressive potential, e.g. CD4+ T-cells expressing FOXP3 transcription factor, has been suggested to be associated with tumor progression and unfavorable prognosis." (PMID 22471961, 2012). "However, we observed a small but significant increase in CD69 expression in activated CD4+ T cells, when cells were stimulated in vitro after in vivo tumor challenge." (PMID 23144743, 2012). "Interestingly, we observed a robust CD4+ T-cell response when neu-expressing tumor-lysate-pulsed DCs were used as the antigen source." (PMID 22397502, 2012). "Within the B16 tumor, we found about 50% of the Foxp3+CD4+ TILs expressed Tim-3." (PMID 22363469, 2012). "In addition, Dz13 mediated tumor regression was prevented by the administration of CD4 or CD8 antibodies, which depleted the mice of the respective T cell subsets." (PMID 22805148, 2012). "Besides rendering other immune cells tumoricidal, CD4+ T cells have the capability to mediate direct tumor destruction." (PMID 22400040, 2012). "Therefore, we believe that our findings that MUC1-specific Treg cells suppress IL-2 production from MUC1-specific CD4+ T cells provide important information in tumor immunity." (PMID 23028615, 2012). "This combination of both high CD8 and CD4 effector to Treg ratios within the tumor represents the conversion of the normally suppressive tumor microenvironment to a more pro-inflammatory state which is more permissive for immune-mediated tumor rejection." (PMID 21559358, 2011). "Using a comparative approach analyzing different tumor subtypes from hematologic as well as epithelial origin, we demonstrate that all independent cancer patient groups studied uniformly show an expanded pool of CD4+CD127lowFOXP3+ Treg cells." (PMID 21904560, 2011). "Second, tumor specific CD4+ T cells can be generated by introducing MHC class I restricted TCRs." (PMID 21892941, 2011). "It has been shown that irradiated tumor cells in a vaccine expressing murine GM-CSF have been demonstrated to stimulate potent, long-lasting, and specific anti-tumor immunity, requiring both CD4+ and CD8+ cells." (PMID 24213115, 2011). "Flow cytometry data were supported by costaining of tumor sections for CD1d and CD4 or NK.1.1." (PMID 21779410, 2011). "In addition, tumor-infiltrating T cells have been shown to exhibit an enriched population of CD4+, CD25+, FoxP3+ regulatory T cells (Tregs)." (PMID 22190972, 2011). "For the generation of tumor specific CD4+ T cells two different strategies can be applied." (PMID 21892941, 2011). "In order to obtain sufficient numbers of tumor-specific CD4+ Th1 cells one may make use of adoptive T-cell transfer protocols or apply strong vaccines." (PMID 22176642, 2011). "Finally, tumor-infiltrating macrophages were reported to attract IL-17+ CD4 T cells in liver carcinoma, thereby sustaining inflammation and supporting tumor promotion." (PMID 22176642, 2011). "Effective immunotherapy is dependent on the presence of both tumor specific CD4+ and CD8+ T cells." (PMID 21892941, 2011). "The frequency of activated CD4+ T cells trended higher on day 26 post-tumor injection." (PMID 21232138, 2011).
tumor (continued). "Furthermore, 13.9% of the tumor in the Ctrl group contained between 11 and 50 CD4+ cells per microscopic field compared to 4.3%, 6.2% and 1.8% respectively for the mice in which IL-18, IFN-γ, or both were neutralized." (PMID 21935389, 2011). "However, CD4 depletion on days 4 and 10 of tumor growth induced significant priming of CD8 T cells specific for TRP-2180–188, as compared with an irrelevant peptide control." (PMID 22046294, 2011). "Again, priming of CD8 T cells only occurred in tumor-bearing mice that were treated with anti-CD4." (PMID 22046294, 2011). "The authors observation that a low density of tumor-infiltrating CD4+ and T-bet+T lymphocytes were present in tumors poorly infiltrated by DCLamp+ mature DC provides additional supportive evidence for the prognostic importance of an adaptive immune reaction to a solid tumor." (PMID 21559281, 2011). "Recently, we evaluated the occurrence of tumor-antigen specific T cells or antibodies after RF ablation in 55 cancer patients and found an increase in antigen-specific antibodies, and CD4+ or CD8+ T cells in several individuals receiving RF ablation alone or shortly after chemotherapy." (PMID 22242035, 2011). "Importantly, we observed a substantial increase of tumor-infiltrating CD4+CD25+ Tregs in both frequency and quantity, in agreement with previous findings." (PMID 21935436, 2011). "In accordance with this NK-like phenotype and as previously reported, CD8α+ and DN iNKT cells displayed more potent cytotoxicity than CD4+ iNKT cells against a number of CD1d+ tumor cell lines, with consistently higher proportions expressing cell-surface CD107a and killing target cells." (PMID 22174854, 2011). "A high proportion of the tumor-infiltrating CD4+ T cells from this model produce IL-13 and IFNγ." (PMID 21281484, 2011). "Nonetheless, the multi-step analysis of dominant CDR3 in the primary tumor, in sorted CD4+ cells and after establishment of lymphoblastoid cell lines ex vivo are important in confirming the capacity of the identified large clones to express a tumor capability." (PMID 21573129, 2011). "It is now generally accepted that this is mostly due to poor tumor-specific MHC class II-restricted CD4+ T helper generated in tumor-bearing hosts and that Th cells are required for priming and clonal expansion of specific CTL following reencounter with antigen." (PMID 22110523, 2011). "The goal of the present study was to assess whether STEAP and EZH2 could function as TAAs for LC, capable of generating anti-tumor CD4 T-cell responses." (PMID 22053850, 2011). "The vaccine induced antibodies specific toward tumor endothelial cells and the in vivo anti-tumor effect could be eliminated by depletion of CD4+ T-cells." (PMID 21385454, 2011). "Notably, elevated proportions of CD4+CD25+ Treg in the total CD4+ T cell populations are present in the tumor microenvironment of various types of cancer where they mediate immune suppression via down regulating the functions of CD4+, CD8+, NK and NKT cells." (PMID 21943203, 2011). "CD4+ T-cell subsets play important and potentially opposite roles in tumor immunosurveillance." (PMID 21829534, 2011). "Adoptive transfer of CD4 T cells populations into B16-OVA tumor-bearing mice." (PMID 22112546, 2011). "In addition, although the tumor draining lymph nodes of IL-18-treated mice had fewer CD4+ T cells, CD8+ T cells and NK cells per lymph node, they represented a higher percentage of lymph node cellularity than those of the αIL-18 group." (PMID 21935389, 2011). "In our experiments, the decline in the number of Tregs, the increase in the ratio of CD8+ T cells to FoxP3+ CD25+ CD4+ Tregs and the lymphopenic environment after cyclophosphamide treatment favor enhanced priming of tumor-specific immune responses during vaccination." (PMID 21859450, 2011). "Likewise, αCTLA-4 played a critical role in allowing proliferation of tumor infiltrating CD4+ effectors." (PMID 21559358, 2011).
tumor (continued). "IL-12 leads to differentiation of CD4+ cells in Th1 subtype which is effective in tumor rejection." (PMID 22046194, 2011). "We previously showed that CD4+ T cells progressively infiltrate the eye after tumor inoculation." (PMID 21949734, 2011). "Besides help in CD8+ T cell priming and maintenance, CD4+ T cells have been shown to recruit and activate various cell populations into the tumor environment, provide bystander mediated killing, and affect angiogenesis." (PMID 24212804, 2011). "Treg expansion observed during tumor progression may result from the proliferation of nTreg or from the conversion of CD4+CD25−FoxP3− T cells into CD4+CD25+FoxP3+ iTreg." (PMID 22110524, 2011). "Initial studies suggested that CD4+ and CD8+ T cells mediated GM-CSF-stimulated antitumor immunity, but recent models using CD1d deficient mice support a critical role for NKT cells in GM-CSF anti-tumor immune responses." (PMID 24213115, 2011). "Furthermore, IL-17 up-regulated elaboration of a variety of proangiogenic factors by fibroblasts as well as tumor cells revealing a novel role for IL-17 as a CD4 or γδT cell-derived mediator as a tumor promoter by inducing angiogenesis and tumor growth." (PMID 21943203, 2011). "We have previously demonstrated that CD8 T cells primed by CD4 T cell depletion in B16 tumor-bearing hosts develop into functional memory after surgical tumor excision, although details of CD4 T cell repopulation during the period of memory development had not been explored." (PMID 22046294, 2011). "Notably, even total depletion of CD4 T cells, beginning 2 days prior to tumor inoculation, induced concomitant tumor immunity in these mice." (PMID 22046294, 2011). "TCR transgenic CD4+ T cells without the addition of CD8 showed hardly any cytokine production after stimulation with the tumor cell lines encoding the HPV16E711-20wt and HPV16E711-20V minigene (data not shown)." (PMID 21892941, 2011). "Conditioning with cyclophosphamide injected one day before cryoablation led to increased IFNγ production of tumor-antigen specific CD4+ T cells in a mouse colon cancer model as detected in intracellular cytokine staining, enhanced survival and even some complete remission." (PMID 22242035, 2011). "The smaller oligoclonal CD4+ cells may represent an anti-tumor response, although on one occasion a low frequency clone was transformed and expanded after culture." (PMID 21573129, 2011). "In addition, CD8+ T cells were present in high concentrations in both tumor tissues while CD4+ T cells were at a much higher concentration in Caski-cell tumors than in HeLa-cell tumors." (PMID 21649881, 2011). "Similarly, combination therapy additively increased the percentage of IFN-γ,TNF-α double producing CD4+ effectors in the tumor." (PMID 21559358, 2011). "Moreover increasing evidence suggests that infiltration of IL-17-producing CD4+ T cells regulates tumor progression." (PMID 21949734, 2011). "However, sequence analysis revealed smaller secondary clones of expanded CD4+ T cells in most tumors (∼10% of the CDR3 sequences) and the outgrowth of one of these during ex vivo culture indicates the tumor potential of sub-dominant CD4+ clones." (PMID 21573129, 2011). "Histological evidence indicates that anti-CTLA-4 activates the tumor vasculature and increases proliferation and infiltration of tumors by CD4+ and CD8+ (FoxP3-) effector cells, thereby increasing the ratio of effector T cells to Tregs in the tumor microenvironment." (PMID 21281484, 2011). "In experimental studies, total tumor destruction by thermal ablation protected animals from further tumor challenge while partial tumor removal by thermal ablation resulted in significant residual tumor inhibition and systemic tumor specific CD4+ and CD8+ T-cell induction compared to resection." (PMID 21619693, 2011). "Moreover, the CD4+CD25+ T cells in tumor-draining lymph nodes declined from stage I to IV, suggesting they were preferentially recruited to the tumor mass." (PMID 20146807, 2010).